BDKRB1 (bradykinin receptor B1)
Diseases named in the same sentence as BDKRB1 in open-access papers (continued):
Sharing a sentence is not in itself a finding about the gene and the disease.
cancer (27 papers, 2012 to 2026). A tumor composed of atypical neoplastic, often pleomorphic cells that invade other tissues. "Tumors with high BDKRB1 expression exhibited immunosuppressive microenvironmental features, including enrichment of cancer-associated fibroblasts and reduced estimated CD8+ T-cell infiltration, despite concurrent activation of inflammatory signaling pathways." (PMID 42088621, 2026). "The activation of BDKRB1 leads to the activation of macrophages, dendritic cells, and other cells in the tumor microenvironment, which have angiogenic properties and is related to the proliferation of malignant tumors." (PMID 36785669, 2023). "BDKRB1 antagonists may interfere less with housekeeping functions and hence could be attractive compounds to treat selected types of cancers." (PMID 32182968, 2020). "CALM1/CALM2/CALM3, the latent IPF-features are the known downstream targets of KNG1 (ligand)—BDKRB1 (receptor) signaling (KEGG: hsa05200, Pathways in cancer)." (PMID 38081956, 2023). "In this study, we have not examined BDKRB1 expression in other culture cell lines including cancer cell lines." (PMID 31523172, 2019). "Similarly, we found that BDKRB1/2 and RXFP2/3 in module 3 have high prognostic significance in five cancer types." (PMID 28676692, 2017).
tumor (22 papers, 2012 to 2026). "BDKRB1, or Bradykinin Receptor B1, has been implicated in promoting the activation of tumour-associated macrophages, thereby facilitating tumour progression and migration." (PMID 39903772, 2025). "Meanwhile, the expression level of hub genes BDKRB1, NMUR2, PMCH, and SAA1 in pRCC tissues was significantly positively correlated with tumor stage, lymph node metastasis, and the histopathology grade of pRCC." (PMID 36785669, 2023).
infection (17 papers, 2013 to 2025). The state of being infected such as from the introduction of a foreign agent such as serum, vaccine, antigenic substance or organism. "In addition, for infections, even with an increase in the BDKRB1 gene expression, the cytokine production pathways, neutrophil migration, and activation levels for several cell-signalling pathways might be compromised." (PMID 27293319, 2016). "In particular, some genes involved in immune/inflammatory responses and infection (e.g., IL19, MAPK15, and SERPINB10) and components of a complement system (e.g., C4B, VTN, BDKRB1, and C4BPA) have not been previously reported regarding their expression and functions in human omental adipose tissue." (PMID 30816281, 2019).
BDKRB1 also shares sentences with these, for which no sentence is quoted: Hypertension (14 papers); Insulin resistance (11); Obesity (9); Arthritis (7); Hyperglycemia (7); renal fibrosis (7); diabetic retinopathy (6); Sepsis (6); Stroke (6); asthma (5); cardiac hypertrophy (5); cardiac ischemia (4); lung carcinoma (4); amyloidosis (3); angioedema (3); Autoimmunity (3); brain ischemia (3); cognitive deficit (3); colon cancer (3); colorectal cancer (3); diabetic neuropathy (3); endothelial dysfunction (3); fibrosis (3); glomerulonephritis (3); gout (3); inflammatory bowel disease (3); ischemia (3); kidney (3); kidney damage (3); prostate carcinoma (3).
A further 103 diseases each share a sentence with BDKRB1 in 3 papers or fewer.